SEMA5A (semaphorin 5A)
Diseases named in the same sentence as SEMA5A in open-access papers (continued):
Sharing a sentence is not in itself a finding about the gene and the disease.
tumor (continued). "Notably, genes such as NRG1, SAMD13, MFAP3L, SALL1, ZNF704, SEMA5A, and HLA-DQB1 were identified as having altered expression patterns, potentially reflecting the diverse roles of FGFRS in tumor biology." (PMID 39676867, 2024). "In mechanism exploration, we discovered that SEMA5A-PLXNB3 axis efficiently facilitated the Warburg effects via upregulating cell stress-related genes and glycolysis function involved key enzymes, thus promoting tumor cells growth." (PMID 36741230, 2023). "To our surprise, we did not observe a difference in tumor incidence, growth or morphology between SEMA5A knockdown and Control cells." (PMID 30577767, 2018). "Similar to SEMA5A expression in human PC tissues, localization of Sema5A expression was observed on membrane of tumor cells with no staining in surrounding stroma." (PMID 29464045, 2018). "We did not observe a difference in tumor incidence and growth between SEMA5A knockdown and Control cells." (PMID 30577767, 2018). "Localization of SEMA5A expression was mainly observed on the membrane of tumor cells with no staining for surrounding stroma." (PMID 29464045, 2018). "Moreover, localization of SEMA5A expression was on the membrane of tumor cells with no positive staining in surrounding stroma." (PMID 29464045, 2018). "In the univariate analysis, tumor grade (P < 0.001), FIGO stage (P < 0.001), LNM (P < 0.001), presence of lymphatic invasion (P < 0.001), VEGF-C expression (P < 0.001), LMVD (P < 0.001), and SEMA5A expression (P = 0.004) were significant prognostic factors for OS." (PMID 29977159, 2018). "SEMA5A expression was localized on tumor cells with no staining in the surrounding stroma." (PMID 29464045, 2018).
cancer (28 papers, 2012 to 2026). A tumor composed of atypical neoplastic, often pleomorphic cells that invade other tissues. "Several genes associated with cancer cell motility, including SEMA5A, PDGFRB, TGFB2, CXCR4, SNAI1, ICAM1, and NEDD9, were decreased in shGPR81 cells." (PMID 35428832, 2022). "In the future, SEMA5A-Plexin-B3-specific signal transduction and cell signaling, particularly in relation to the cancer stemness feature and whether the loss of Plexin-B3 is mechanistically required for the extra-pancreatic spread, needs evaluation." (PMID 33669221, 2021). "Most importantly, some studies have revealed that the functions of Plexins in cancers are regulated by semaphorins, including Sema3C, Sema4D, and Sema5A." (PMID 37901456, 2023). "Sema3E, Sema4D, and Sema7A were shown to contribute to EMT, whereas Sema3B, Sema3F, and Sema5A inhibited EMT in cancer cells." (PMID 35775491, 2022). "Since recent literature suggests aberrant genomic expression of axonal guidance cue molecules in cancer, we went ahead and analyzed the copy number variation of SEMA5A in PC cases using The Cancer Genome Atlas (TCGA) Database." (PMID 29464045, 2018). "With an interest to evaluate SEMA5A expression between primary cancer and different metastatic sites, we utilized TMA with 21 cases of PC patients with primary tumor and either one, two or three metastatic sites like liver, diaphragm, and intestine." (PMID 29464045, 2018). "Furthermore, we analyzed the mutation status of ASCC3, JAK1, NFKB1, SEMA5A, NR2C2, CNTF and CREB1 across pan-cancer." (PMID 40881169, 2025). "The expression of the two upregulated DEGs (Cp and Sema5a) was dependent on the cancer type." (PMID 40182023, 2025). "High SEMA5A expression level has been demonstrated in several cancers." (PMID 29977159, 2018). "Moreover, semaphorin-5a has been shown to promote cell proliferation and to inhibit apoptosis in several cancers, raising the possibility that it could promote immunotolerance of foreign Symbiodinium cells." (PMID 28481198, 2017). "Next-generation sequencing targeting 520 cancer-related genes was performed on the pleural effusion samples and revealed 2 novel RET fusions LINCO1264-RET and SEMA5A-RET, concomitant with a common CCDC6-RET." (PMID 36451418, 2022). "We also observed that the secretory form of Sema5A enhances proliferation of endothelial cells and upregulates secretion of angiogenic factors like CXCL8 and VEGF in cancer cells." (PMID 30577767, 2018). "Other miR-143 responsive genes with a miR-143 seed site in their 3'UTR were SEMA5A, SLC35B2 and KLF5 which have all been shown to be up-regulated in cancers and to promote cell proliferation." (PMID 22691140, 2012). "Additionally, the semaphorins 5A and 6A (SEMA5A, SEMA6A) which we identified among the upregulated DEGs have been shown to act as the potential suppressors of cancer migration." (PMID 38383756, 2024). "Possible reasons for these observations can be that lymph node metastasis may represent cancer cells in transition and does not upregulate cell adhesion molecules such as SEMA5A." (PMID 29464045, 2018). "The lack of these cancer stem cell markers, specifically SEMA5A (semaphorin 5A), KITL (KIT ligand, stem cell factor), CAV2 (caveolin 2), EPS8 (epidermal growth factor receptor pathway substrate 8) and PKP4 (plakophilin 4), was associated with acquired resistance to radiation in this study." (PMID 33767581, 2021).
neurodevelopmental disorder (4 papers, 2016 to 2025). A behavioral and cognitive disorder with onset during the developmental period that involves impaired or aberrant development of intellectual, motor, or social functions. "Dysregulation of ErbB2 signaling has been implicated in neurodevelopmental disorders, raising the possibility that ErbB2 may contribute more broadly to abnormalities in neural morphogenesis beyond the context of Sema5A mutations." (PMID 41226692, 2025). "The expression profiles of SEMA5A in the brain indicates that this gene may play an essential role in the development of the brain and that dysfunctional SEMA5A may lead to human neurodevelopmental disorders such as EEs." (PMID 31354784, 2019). "Our results provide genetic and functional evidence showing that SEMA5A plays a significant role in the development of the brain and might be involved in several neurodevelopmental disorders, such as EE and ASD." (PMID 31354784, 2019).
neurological diseases (2 papers, 2024). "Our study rationalizes Sema5A associated developmental and neurological disorders and provides mechanistic insights into how multifaceted guidance functions of a single transmembrane cue are regulated by proteoglycans." (PMID 38548715, 2024). "Deleterious missense mutations in the SEMA5A gene are associated with various types of developmental and neurological disorders in humans." (PMID 38548715, 2024). "Further studies may reveal the association of Sema5A with many neurological diseases in addition to ASD and ID." (PMID 38666924, 2024).
peripheral neuropathy (2 papers, 2015 to 2021). A disorder affecting the peripheral nervous system. "Based on the genotype-phenotype correlations of these three CNVs, we consider LAMA2 to be a new potential target gene for peripheral neuropathy, whereas CNTNAP2 and SEMA5A remain potentially pathogenic." (PMID 25648254, 2015).
infection (1 paper, 2018). The state of being infected such as from the introduction of a foreign agent such as serum, vaccine, antigenic substance or organism. "While serum concentrations of SEMA3C and SEMA6D significantly increased with fibrosis stage in both HCV-g1 and HCV-g3 infection, serum concentration of SEMA5A inversely correlated with fibrosis stage in both HCV genotypes." (PMID 30592759, 2018).
SEMA5A also shares sentences with these, for which no sentence is quoted: Cri-du-chat syndrome (3 papers); Parkinson disease (3); systemic lupus erythematosus (3); astrocytoma (2); non-small cell lung carcinoma (2); thyroid cancer (2); Arthritis (1); bacterial diseases (1); bladder cancer (1); chronic pancreatitis (1); colon cancer (1); Diabetes (1); digestive system cancer (1); endometrial cancer (1); fibrosis (1); in situ melanoma (1); infantile spasms (1); metastatic melanoma (1); ovarian carcinoma (1); speech disorder (1).